NKX2-5 (NK2 homeobox 5)
Diseases named in the same sentence as NKX2-5 in open-access papers (continued):
Sharing a sentence is not in itself a finding about the gene and the disease.
atrial septal defect (continued). "Mutations in the cardiac transcription factor, NKX2-5, were identified in families who primarily exhibited non-syndromic atrial septal defects and atrioventricular conduction abnormalities." (PMID 22589735, 2012). "Somatic mutations in NKX2-5 do not represent an important aetiologic pathway in pathologic cardiac development in patients with cardiac septal defects." (PMID 19181906, 2009). "NKX2-5, NOTCH1 and GATA4 have high confidence for nonsyndromic CHD, atrial septal defect (NKX2-5 and GATA4), aortic valve stenosis and tetralogy of fallot (NOTCH1)." (PMID 39567769, 2024). "For example, in the case of atrial septal defect (ASD) and ventricular septal defect (VSD), candidate genes can be counted: NKX2-5, GATA4, TBX20, MYH6, and TBX5, while the pathogenesis of atrioventricular septal defect (AVSD) involves genes, such as PTPN11, KRAS, SOS1, RAF1, and CRELD1." (PMID 34946970, 2021). "Inherited mutations of the Nkx2-5 gene are a common genetic cause of CHD in humans as they can result in an assortment of cardiac malformations, such as right isomerism, atrioventricular (AV) block, ventricular septal defect (VSD), and atrial septal defect (ASD)." (PMID 32548129, 2020). "Although neither Nkx2-5+/-nor Xrn2+/- hearts showed a muscular ventricular septal defect (VSD) at postnatal day 0 (P0), we found a VSD in Nkx2-5+/-Xrn2+/-newborn hearts (n = 3 of 7)." (PMID 27331609, 2016).
Tetralogy of Fallot (20 papers, 2008 to 2025). A congenital cardiac malformation comprising pulmonary stenosis, overriding aorta, ventricular septum defect, and right ventricular hypertrophy. "Approximately 2–4% of all CHDs can be associated with SNPs in the NKX2-5 gene, particularly linked with septal defects (ASDs and VSDs) or outflow tract defects (tetralogy of Fallot, double-outlet right ventricle, and transposition of the great arteries)." (PMID 38397197, 2024). "Twelve distinct mutations in the NKX2‐5 coding region were identified in 18 of 608 patients (3%) including 9 of 201 with Fallot tetralogy, 3 of 71 with ASD secundum, one with truncus arteriosus, one with double–outlet right ventricle." (PMID 30834692, 2019). "Disruption of RXRα was recently associated with the cardiac malformation tetralogy of Fallot, previously associated with mutations in NKX2-5." (PMID 27683156, 2016). "In twins with tetralogy of Fallot (TOF), it has been observed that a good number of genes in cardiac tissue have been linked to differential DNA methylation like the NKX2-5 (NK2 Homeobox 5) and HAND1 (Heart And Neural Crest Derivatives Expressed 1) genes." (PMID 34540478, 2021). "They found one formerly known NKX2‐5 missense variation, heterozygous c.73C>T (p.Arg25Cys), in a 10‐year‐old child with Fallot tetralogy." (PMID 30834692, 2019). "Regarding synonymous variant rs2277923 in NKX2‐5, CT and TT genotypes were presented more frequent in CHD cases (15 ASD, 24 VSD, six PDA, six aortic coarctation and nine Fallot's tetralogy) than control group, as CT genotype was present in 58% and 36% in cases and control respectively." (PMID 30834692, 2019). "Previous study investigated the incidence and prevalence of GATA4, NKX2‐5, gene mutations in a large group of individuals with controtruncal defect (CTD), including 178 patients with tetralogy of Fallot, 13 patients with double–outlet right ventricle (DORV), and 11 patients with truncus arteriosus." (PMID 30834692, 2019). "Mutations in NKX2-5 (5q35.1), GATA4 (8q23.1), ZFPM2 (8q23.1), GATA6 (18q11.2), GDF1 (19p13.11), JAG1 (20p12.2), and TBX1 (22q11.21) have been reported in sporadic cases with tetralogy of Fallot; however, interaction of these genes and FMR1 gene has never been reported." (PMID 28751920, 2017). "NKX2-5, GATA4 and HAND1 are essential for heart development, however, little is known regarding their epigenetic regulation in the pathogenesis of tetralogy of fallot (TOF)." (PMID 24182332, 2013).
heart failure (16 papers, 2011 to 2026). Inability of the heart to pump blood at an adequate rate to meet tissue metabolic requirements. "A recent study has shown that mice with conditional knockout of NKX2-5 develop excessive trabeculation associated with conduction defects and heart failure progression." (PMID 33082984, 2020). "A longitudinal study of cardiac function in adult Nkx2-5 conditional mutant mice demonstrates that excessive trabeculation is associated with complex ventricular conduction defects, progressively leading to strain defects, and, in 50% of mutant mice, to heart failure." (PMID 29979676, 2018). "We proposed that under the regulation of Nkx2-5 and Gtf2b, activation of components of muscle and mitochondrial dysfunction were induced in cardiomyocytes with high Nppa expression, resulting in heart failure by a trans-omics approach." (PMID 33854108, 2021). "Nkx2-5 regulates multiple downstream targets including cMLCK, and perinatal Nkx2-5-KO mice demonstrate more profound heart failure compared to perinatal Mylk3-KO mice, with a 1.44 fold increase of HW/BW ratio at P12." (PMID 27833563, 2016). "TBX5-regulated NKX2-5 is involved in heart formation and development and dysregulated NKX2-5 could lead to heart failure and sudden cardiac death." (PMID 32423033, 2020). "In a previous study, we demonstrated that the conditional deletion of Nkx2-5 in trabecular cells during embryonic development provokes a hypertrabeculated phenotype associated with cardiac hypertrophy, subendocardial fibrosis and severe VCS hypoplasia, which induced heart failure with age." (PMID 37233161, 2023). "Moreover, mice carrying a loss of function allele for NKX2-5 show PR prolongation and heart failure without any apparent morphological defects." (PMID 30840660, 2019). "Genes related to FAO pathways, including CPT1A, were significantly low in expression in the patient (iTAZ) cardiomyocytes, while cardiac failure markers such as NPPA, NPPB, NKX2‐5 were upregulated in the same." (PMID 37533404, 2023). "In our study, inhibition of TBX5 was shown to dysregulate several genes such as DES, NKX2-5, ACTC1, MYH6, ATP2A2 and HSPB7, which further contributed to ICM-related diseases such as failure of heart and degeneration of heart." (PMID 32423033, 2020). "NKX2-5, HSPB7 and BCL2L1 were also involved in failure of heart." (PMID 32423033, 2020). "NKX2-5 and MYH6 were involved in failure of heart and arrhythmia, respectively." (PMID 32423033, 2020). "In contrast, we found that overexpressed Myc bound both the promoter region and body of many cardiac-specific genes including transcription factors (Gata4, Gata6, Tbx20, Nkx2-5), structural genes (Actc1, Pln), or heart failure related genes (Nppa, Nppb), but did not induce Pol II recruitment." (PMID 27346836, 2016).
ventricular septal defect (16 papers, 2017 to 2025). The presence of a defect (opening) in the septum that separates the two ventricles of the heart. "Mutations in NKX2-5 have been associated with ventricular septal defects (VSD), hypoplastic left heart syndrome (HLHS), atrial septal defect and tetralogy of Fallot (TOF)." (PMID 40917916, 2025). "NF1 and GLI3 are both linked with multiple forms of CHDs, including atrial and ventricular septal defects, which are common forms of CHDs that are also associated with CHD genes such as NKX2–5 and TBX5." (PMID 40857331, 2025). "GATA4-NKX2-5 physical and functional interactions have been confirmed in both mouse models and human cardiomyocytes, with human genetic studies showing digenic inheritance patterns involving GATA4 and NKX2-5 variants in families with atrial and ventricular septal defects." (PMID 40917916, 2025).
cardiac hypertrophy (14 papers, 2011 to 2024). "Activated GATA4 is known to associate with other transcription factors such as serum response factor (SRF) and NK2 homeobox 5 (NKX2-5) to initiate the pathway for cardiac hypertrophy-related gene expression." (PMID 38255639, 2023). "Meanwhile, CAMTA2 can also bind to NKX2-5 and participate in the pathogenesis of cardiac hypertrophy." (PMID 33195237, 2020). "Camta2 has been shown to interact with Nkx2-5 and promote cardiac hypertrophy in mice." (PMID 24826987, 2014). "Also notably, expression of the cardiogenic transcription factor Nkx2-5 was significantly increased in the ventricles of Ahr-/-, and low- and high-dose TCDD-exposed Ahr+/+ females as previously reported in cardiac hypertrophy." (PMID 26555816, 2015).
thyroid dysgenesis (13 papers, 2010 to 2025). "CH due to thyroid dysgenesis has also been linked to pathogenic variants of the nucleotide kinase 2, homeobox 5 (NKX2-5) gene, which can also cause sudden cardiac death from ventricular arrhythmia." (PMID 36468928, 2022). "Deletion of NKX2–5 in mice causes thyroid agenesis, suggesting that this transcription factor plays an important role in thyroid development, but to what degree this finding extends to humans is not clear." (PMID 29026407, 2017). "The presence of mutations in the NKX2-5 was to date detected in several patients with thyroid developmental defects, namely thyroid agenesis [p.R25C], hypoplasia [c.63A>G (p.E21E), c.73C>T (p.R25C), c.293G>A (p.S98N), c.676G>A (p.D226N)], and ectopy [p.R25C, p.A119S, p.R161P]." (PMID 35328834, 2022). "Heterozygous variants in NKX2–5 are found in some individuals with thyroid dysgenesis; however, the pathogenicity of these variants is unclear since they do not consistently cosegregate with thyroid disease in families and some may not impair protein function in vitro." (PMID 29026407, 2017). "For the first time, NKX2-5 gene variants were found in two siblings with THA, providing evidence for its potential contribution to the pathogenesis of this type of thyroid dysgenesis." (PMID 35328834, 2022). "Additionally, 21.21% (28/132) of mutations were related to thyroid dysgenesis [TSHR (n = 19), TTF1 (n = 5), TTF2 (n = 1), PAX8 (n = 2), and NKX2-5 (n = 1)]." (PMID 30420871, 2018). "Furthermore, given the wealth of published evidence, we suggest that NKX2-5 mutations do not play a major pathogenic role in thyroid dysgenesis, and that genetic testing of NKX2-5 in TD is not warranted." (PMID 23285148, 2012). "Additionally, we reviewed the current literature on the topic, showing that there is no clear evidence for a major pathogenic role of NKX2-5 mutations in thyroid dysgenesis." (PMID 23285148, 2012). "Besides p.A119S, two other NKX2-5 mutations [i.e. c.73C>T (p.R25C) and c.482G>C (p.R161P)] were found in thyroid dysgenesis (TD), in patients with or without cardiac anomalies, to suggest NKX2-5 mutations to have variable penetrance and a broader impact in organogenesis and pathophysiology." (PMID 24376681, 2013).
atrial fibrillation (12 papers, 2014 to 2023). A disorder characterized by an electrocardiographic finding of a supraventricular arrhythmia characterized by the replacement of consistent P waves by rapid oscillations or fibrillatory waves that vary in size, shape and timing and are accompanied by an irregular ventricular response. "Common variants of NKX2‐5 influence the PR interval and the risk of atrial fibrillation; the latter association has also been reported in the Nkx2‐5+/− mouse." (PMID 24771692, 2014). "RBM20 is also likely to be an important regulator of the pulmonary myocardium molecular phenotype, is associated with NKX2-5 expression, and could be an important therapeutic target in atrial fibrillation." (PMID 28720711, 2017). "Trait associations were found for five loci: the SNV at TMEM44 was associated with diastolic blood pressure, SLC27A6 with red cell distribution, NKX2–5 with heart rate and atrial fibrillation, and finally NUFIP2 with mean platelet volume." (PMID 34274964, 2021). "Numerous studies now indicate that polymorphisms in genes encoding the cardiac transcription factors NKX2-5 and PITX2C increase susceptibility to atrial fibrillation, suggesting the potential involvement of disrupted gene networks in this disorder." (PMID 28720711, 2017). "As a whole, our data imply that regulatory polymorphisms which alter expression levels of upstream regulators of this gene network (such as Nkx2-5, Mef2a, SRF, Nostrin, Znf451, and Ttn) might predispose to atrial fibrillation." (PMID 28720711, 2017). "However, mutations in genes encoding the transcription factors Nkx2-5, Pitx2c, and GATA6 are all associated with atrial fibrillation; these genes are known to be required for cardiovascular development." (PMID 28720711, 2017). "Furthermore, GWAS of multiple cardiac traits, such as atrial fibrillation and PR interval, identified loci associated with embryonic development-associated genes and genes whose mutations are known to cause serious heart defects, such as TTN, GATA4, MYH6, NKX2-5, PITX2, and TBX52–4." (PMID 36854752, 2023). "Namely, the down-regulation of NKX2-5 indicates a deviation from cardiac tissue, accompanied by electrical remodelings, i.e., the down-regulation of KCNH2 and SCN2B, resulting in the formation of atrial fibrillation." (PMID 37445678, 2023).
Arrhythmia (11 papers, 2009 to 2025). Any cardiac rhythm other than the normal sinus rhythm. "Mutations in the transcription factor Nkx2-5 have been implicated in a high prevalence of developing ventricular conduction defects or arrhythmias with age." (PMID 37233161, 2023). "It was also shown that in human patients with mutations in Nkx2-5 often have arrhythmias." (PMID 36751888, 2023). "Moreover, patients carrying mutations in NKX2-5 present a large spectrum of congenital heart diseases frequently associated with conduction disturbances or arrhythmias, and long-term follow-up reveals a high incidence of sudden cardiac death in these patients with aging." (PMID 37233161, 2023). "Furthermore, downstream genes (MYH6, MYH7, TNNT2, NKX2-5, and CCND1) regulated by SFRP4 partake in ICM-related diseases like HF and arrhythmias." (PMID 40066352, 2025).
cardiomyopathy (11 papers, 2016 to 2024). A disease of the heart muscle or myocardium proper. "Understanding the mechanisms guiding Nkx2.5-dependent cardiac regeneration will have an impact on the management of patients with CHD or cardiomyopathies associated with NKX2-5 mutations." (PMID 35624100, 2022). "We identified novel DNVs in diagnostic-grade genes (RYR2, TNNT2, PTPN11, MYH7, LZR1, NKX2-5), and five cases harbouring a combination of prioritised variants, suggesting that oligogenic inheritance and genetic modifiers contribute to cardiomyopathies." (PMID 36357925, 2022). "Interestingly, Six1 has been recently found to be deregulated in cardiomyopathy induced by Nkx2-5 point mutation or in human patients." (PMID 29979676, 2018). "Major genes known for their role in LVNC or other cardiomyopathies and genes previously reported in Nkx2-5 mutants were found to be deregulated in both mutants." (PMID 29979676, 2018). "We identified further genes that regulate the development of trabeculation (NKX2-5, TBX20, HAND2, NRG1, NOTCH1 and DTNA) and those with evidence of involvement in cardiomyopathies (CRYAB and RIT1 (ARHGEF2))." (PMID 39567769, 2024).
atrioventricular block (10 papers, 2015 to 2025). A heart block that is initiated in the atrioventricular node. "This case report describes a novel NKX2-5 mutation, Tyr274Ser, identified in a patient with progressive AV block." (PMID 40255339, 2025). "In addition, introduction of dominant negative Nkx2-5 variants in the mouse causes similar phenotypes to those observed in patients with NKX2-5 mutations, such as AV block and atrial septal anomalies." (PMID 29636455, 2018). "Impairments in the NKX2-5 gene lead to conduction abnormalities, particularly atrioventricular block, which can ultimately have a fatal outcome." (PMID 41153710, 2025). "Moreover, increased PR intervals, indicative of 1st degree atrioventricular block in accordance with the atrial deletion of Nkx2-5, were evidenced as previously reported in Nkx2-5 mutants." (PMID 29979676, 2018).
congenital heart defects (8 papers, 2009 to 2023). "The transcription factor NKX2–5 is expressed in the developing heart and thyroid, and NKX2–5 mutations are associated with congenital cardiac abnormalities." (PMID 29026407, 2017).
thyroid (8 papers, 2018 to 2025). "The genes associated with thyroid morphogenesis such as NKX2-1, NKX2-5, PAX8, FOXE1, and thyroid-stimulating hormone receptor (TSHR) have been reported to be involved in thyroid dysgenesis." (PMID 32394050, 2020). "While the phenotype of Nkx2-6 and Nkx2-3 null mice does not suggest a thyroid defect, Nkx2-5-null mice present with a small thyroid bud expressing Nkx2-1, Foxe1 and Pax8 at E9.5, pointing to a role for Nkx2-5 in thyroid organogenesis." (PMID 33959098, 2021).
congenital hypothyroidism (7 papers, 2010 to 2022). A thyroid hormone deficiency present from birth. "Additionally, in a recent study mutations in NKX2-5 were reported in a small proportion of patients with persistent congenital hypothyroidism." (PMID 23285148, 2012). "However, the NKX2-5 gene has been analyzed in over 460 congenital hypothyroidism patients to date, but no additional mutations were identified." (PMID 23285148, 2012).
dilated cardiomyopathy (7 papers, 2011 to 2022). Cardiomyopathy which is characterized by dilation and contractile dysfunction of the left and right ventricles. "Similarly, a mutation in the transcription factor NKX2-5 leads to adult-onset dilated cardiomyopathy and expression of such a specific mutant form of NKX2 in COS-7 cells or HL-1 cardiomyocytes causes UPS impairment." (PMID 36111332, 2022). "Moreover, in patients with dilated cardiomyopathy, there is an altered methylation pattern in the regulatory regions of cardiac development genes, such as T-box protein 5 (TBX5), heart and neural crest derivatives expressed 1 (HAND1), and NK2 homeobox 5 (NKX2.5)." (PMID 31649728, 2019).
T-cell acute lymphoblastic leukemia (7 papers, 2009 to 2021). Acute lymphoblastic leukemia of T-cell origin. "Three members of the NK-like subfamily of homeobox genes (NKLs), TLX1, TLX3 and NKX2-5, are implicated in T-cell acute lymphoblastic leukemia (T-ALL)." (PMID 19835636, 2009). "Another group of T-cell acute lymphoblastic leukemia (T-ALL)-associated oncogenes are homeobox genes and includes members of the NK-like family, TLX1/HOX11, TLX3/HOX11L2 and NKX2-5/CSX, and of the clustered homeobox genes, HOXA5, HOXA9, HOXA10 and HOXA11." (PMID 20565746, 2010). "Aberrant activation has been reported in acute T-cell leukemia, whereby MEF2C is directly regulated by an oncogenic homeodomain TF, NKX2–5, or targeted by genomic deletions of non-coding regulatory regions." (PMID 26473286, 2015). "T-cell acute lymphoblastic leukemia (T-ALL) cells represent developmentally arrested T-cell progenitors, subsets of which aberrantly express homeobox genes of the NKL subclass, including TLX1, TLX3, NKX2-1, NKX2-5, NKX3-1 and MSX1." (PMID 28151996, 2017).
acute lymphoblastic leukemia (6 papers, 2009 to 2023). Leukemia with an acute onset, characterized by the presence of lymphoblasts in the bone marrow and the peripheral blood. "Nkx2–5 is dysregulated in acute lymphoblastic leukemia (ALL), hepatocellular carcinoma (HCC), and T cell neoplasias, methylated in prostate adenocarcinoma, hyper-methylated in salivary gland adenoid cystic carcinoma." (PMID 38110859, 2023).
diabetes (5 papers, 2014 to 2024). "Self-assembled organoids have been used to investigate heart field progenitor cell markers, the effects of gene knockouts (e.g., NKX2-5), the response to isoproterenol compared to that observed in vivo, cryoinjury studies, and disease modeling (pregestational diabetes)." (PMID 34572490, 2021).
Hyperglycemia (5 papers, 2017 to 2025). An increased concentration of glucose in the blood. "Maternal hyperglycemia and metabolic syndromes during pregnancy may influence the expression of cardiogenic transcription factors (e.g., GATA4, NKX2-5), thereby predisposing the fetus to structural cardiac anomalies." (PMID 41383574, 2025).